IL1B (interleukin 1 beta)
Diseases named in the same sentence as IL1B in open-access papers (continued):
Sharing a sentence is not in itself a finding about the gene and the disease.
tumor (continued). "Multiple in vitro studies have demonstrated that the process of epithelial-to-mesenchymal transition (EMT), a pivotal step for cancer progression with tumor invasion and distant metastasis, is activated by proinflammatory cytokines including TNFα, IL-6, IL-8, and IL-1β." (PMID 37628724, 2023). "Tumor-derived IL-1β activates γδT-cells, which in turn secrete IL-17." (PMID 37511306, 2023). "Overexpression of IL‐1β showed minimal effects on tumor cell growth in vitro." (PMID 37092583, 2023). "The results position these cancers as favorable candidates for anti-IL-1β therapy, and versican as a diagnostic and prognostic biomarker, as well as a therapeutic target in this tumor category that comprises 9% of all human cancers, alone or in combination with anti-IL-1β agents." (PMID 36980752, 2023). "Here, we found that the pro‐inflammatory cytokine IL‐1β could be triggered and released from Mφ by lactate derived from tumor cells." (PMID 37009412, 2023). "Thus, VCAN-driven IKKβ activation mediates NF-κB signaling, IL-1β expression, differentiation, and pro-tumor function of macrophages." (PMID 36980752, 2023). "Although the majority of published studies suggesting a tumor promoting role for IL-1β, several studies have also demonstrated a tumor inhibiting effect, and the impact of IL1β signalling may vary depending on the cell type and the microenvironment." (PMID 37065483, 2023). "Thus, IL‐1β and lactate mediate the feedback crosstalk between Mφ and tumor cells to weaken antitumor immunity, designing a synergistic antitumor effect when ICB is combined with IL‐1β blockade." (PMID 37009412, 2023). "Furthermore, MDSCs can induce IL-1β and IL-17 production, signaling between tumor cells and macrophages leading to tumor cell growth and invasion potentiation." (PMID 38093246, 2023). "Our findings demonstrate that curcumin enhances the abscopal effect in a bilateral CT26 tumor-bearing mouse model by suppressing NF-κB and downstream proteins, elevating IL-1β and IL-6, and modulating the overall tumor immune microenvironment, thereby enhancing tumor suppression." (PMID 37242761, 2023). "Although IL-1β is regarded as a marker of M1-like macrophages that activates anti-tumor immunity in some cases, abnormal inflammasome activation in tumor-associated macrophages (TAMs) has been manifested to be a promoter of invasion and metastasis in many kinds of tumors." (PMID 36932407, 2023). "IL-1β depletion in the HCC tumor-bearing mice restores the STC." (PMID 37400621, 2023). "Functionally, the activation of the NLRP3 inflammasome can result in the pyroptotic programmed death of cells and the release of the proinflammatory cytokines IL-1β and IL-18, which can establish inflammatory microenvironmental conditions conducive to tumor growth." (PMID 37885032, 2023). "A few studies demonstrated that the expression of IL-6, IL-8, and IL-1β could promote the tumor relapse and metastasis." (PMID 37437020, 2023). "We found the IL-1β scores to be significantly higher in CAFs when compared to NFs, suggesting that increased IL-1 signaling is also occurring in vivo in CAFs within the tumor tissues." (PMID 37460545, 2023). "We figured out a loop composed of tumor cells, lactate, Mφ, IL‐1β, and PD‐L1 above." (PMID 37009412, 2023). "In NSCLC, BRAFV600E promotes the generation of interleukin (IL), such as IL-1α and IL-1β, hence repressing the recognition and killing capacity of tumor-specific CTLs, partially through the upregulation of PD-1 ligands, PD-L1, and PD-L2, and via secretion of cyclooxygenase (COX-2)." (PMID 37345046, 2023). "Furthermore, inhibiting IL-1β can increase the percentage of activated cytotoxic T-cells, leading to improved tumor suppression." (PMID 37511306, 2023).
tumor (continued). "We hypothesized that the IL1B features driving a new tumor subtype that could be reflected in their OS time and could be predicted using the radiomics method." (PMID 36969073, 2023). "We found that all three cell subsets secreted higher level of IL-1β when stimulated with fecal contents extracted from tumor-bearing mice than from control mice, suggesting the tumor-induced microbiota alteration is involved in the upregulation of IL-1β production." (PMID 37400621, 2023). "Moreover, residual tumor-promoting activity in the skin of TNF-α−/− mice was associated with induction of IL-1α and IL-1β gene expressions." (PMID 37097392, 2023). "Moreover, we demonstrated that systemic depletion of both type I IFNs and IL‐1β cytokine abrogated tumor regression in mice bearing the Arf1‐ablated tumor cells." (PMID 37786300, 2023). "IL-1β blockade has been shown to reverse immunosuppression and has been shown to exhibit synergy with PD-1 inhibitors to promote the elimination of several tumor types, including breast, pancreatic, and renal tumors." (PMID 37106440, 2023). "In KO mice where Il1b was absent in both the tumor and TME cells, Il1b loss prolonged the survival of PDGFB-driven tumor-bearing mice in a sex-independent manner." (PMID 37733448, 2023). "However, MCC950 significantly reversed the tumor-induced upregulation of Nlrp3 and Il1b gene expression." (PMID 37749707, 2023). "Although IL‐1β secreted by Mφ upregulates PD‐L1 expression in tumor cells, the molecule that induces IL‐1β secretion from Mφ is still unknown." (PMID 37009412, 2023). "To determine whether IL‐1β was secreted by Mφ or tumor cells, we knocked down IL‐1β in tumor cells in the co‐culture system." (PMID 37009412, 2023). "Similarly, NLRP3 is overexpressed in tissues of head and neck squamous cell carcinoma resulting in increased IL-1β concentration in blood, spleen, draining lymph nodes, and tumor tissues." (PMID 36932407, 2023). "Paradoxically, IL-1β promotes tumor immune evasion and tumor progression." (PMID 36845555, 2023). "Pro-inflammatory bacteria stimulate the production of cytokines and chemokines, such as IL-6, IL-8, IL-1b, and TNF-α, which recruit and activate various immune cells, including tumor-associated macrophages (TAMs), T cells, and myeloid-derived suppressor cells (MDSCs)." (PMID 37760801, 2023). "In addition, we demonstrate that IL-1β stimulated fibroblasts induce tumor growth in 3D organotypic tumor assays, an effect which is abrogated upon IL−1 signaling blockade." (PMID 37460545, 2023). "Immune cells involved in tumor suppression, T cells, dendritic cells (DCs), epithelial cells, neutrophils, macrophages, and other antigen-presenting cells (APCs) express IL-1 receptors (IL-1R and IL-1R2) which interact with IL-1β." (PMID 37511306, 2023). "Within the tumor microenvironment, cancer cell interactions with adipocytes and macrophages promote cancer progression through a variety of mechanisms involving oxidative stress, IL-6, IL-1β, STAT3, ERK and CLS." (PMID 36670988, 2023). "As in the primary tumor, we also report that select M1 macrophage markers were reduced with emodin in wounded mice; emodin‐wounded mice exhibited reduced expression of IL‐6 (p = 0.0188) and a reduction in IL‐1β (p = 0.1193) compared to that of PBS." (PMID 37821408, 2023). "IL-1β is abundant in the tumor microenvironment, promoting tumor growth by recruiting monocytes." (PMID 37371050, 2023). "Unlike propofol, sevoflurane exposure resulted in bigger tumour size, shorter survival time (assessed with the clinical endpoints, including body weight loss > 20% and tumour volume > 70 mm3), higher HGF, HIF1α, IL1β and TNFα expressions, and lower E-cadherin and TIMP-2 expressions." (PMID 35953652, 2023).
tumor (continued). "Inflammasome components can be expressed and activated by various stimulators in cancer cells, fibroblasts, and macrophages resulting in the secretion of IL-1β and IL-18, which further modulates the expression of PD-L1 in tumor cells and recruitment of immune-suppressive cells in TME." (PMID 36932407, 2023). "Therefore, reduction in tumor-promoting TAMs alone cannot offset the combined detrimental effects of lymphoid and IFN loss in Il1a–/–;Il1b–/–;Ntv-a mice." (PMID 37733448, 2023). "Moreover, overexpression of Saa3 significantly enhanced pulmonary metastasis of HCC while didn’t affect primary tumor growth in Il1b−/− mice." (PMID 37443052, 2023). "Since IL-1β has been shown to exhibit both pro-tumor and anti-tumor effects, we examined whether the proliferation activities in response to IL-1β were influenced by Il1rn KO." (PMID 37563620, 2023). "However, compared to the isotype treatment, treatments with systemic anti‐IFNAR1 and anti‐IL‐1β antibodies abrogated anti‐tumor effects, as evidenced by significantly increased tumor size and tumor weight of mice bearing the Arf1‐ablated tumor cells." (PMID 37786300, 2023). "However, on the intestinal mucosal surface, the intestinal barrier function and tumor surveillance depend on activation of inflammasome to product active IL1B and IL18." (PMID 36741232, 2023). "In addition, the results of cytotoxicity assay suggested that pre-treatment of tumor cells with IL-1β suppress T cell activity." (PMID 37441079, 2023). "For example, Astragaloside IV, as an active extract of Astragali Radix, could inhibit the growth and proliferation of tumor cells and induce apoptosis of tumor cells, and promote immunity by regulating levels of IL-1β, IL-6, and TNF-α cytokines." (PMID 37907925, 2023). "This difference may be attributed to the secretion of IL‐1β into the microenvironment, where it activates cells in the tumor mesenchyme, including malignant tumor cells." (PMID 37547175, 2023). "This was supported by our functional RNA analysis of the tumour tissue from ever smokers, whereby these patients significantly over-expressed pro-inflammatory genes involved in Nf-ĸB signalling, in particular TNFα and IL-1β." (PMID 37398676, 2023). "During chronic inflammation, the TME is enriched with inflammatory factors secreted by tumor cells, CAFs, and immune cells, such as IL-6, IL-8, IL-1β, IL-10, and IL-17, creating a microenvironment conducive to dormancy escape as well as reactivating cancer cell expansion." (PMID 37173977, 2023). "Furthermore, in triple-negative breast cancer, IL-1β stimulates TAMs recruitment, driving tumour growth and immunosuppression." (PMID 37742025, 2023). "It is possible that tumor-induced Lactobacillus reduction may partially contribute to the elevated IL-1β secretion, as several Lactobacillus species have been implicated to modulate pro-inflammatory responses." (PMID 37400621, 2023). "The presence of bacteria in the pancreas can stimulate resident leukocytes to produce Interleukin-1β (IL-1β), which produces proangiogenic factors in the tumour microenvironment (TME) (e.g., Vascular Endothelial Growth Factor (VEGF), Tissue Necrosis Factor (TNF))." (PMID 38069211, 2023). "In addition, primary PDGFB-driven tumor cells increase CCL2 expression in response to recombinant IL-1β (rIL-1β)." (PMID 37733448, 2023). "Tumor-associated macrophages (TAMs), by secreting many factors, such as TGF-B, TNF-a, IL-1B, and IL-6, may be responsible for inducing the EMT process in CRC." (PMID 37185706, 2023). "In cancer, IL-1β has a pleiotropic effect on cells of the immune system, angiogenesis, proliferation, migration, and metastasis of tumor cells, so its decrease promoted by venom may contribute to its antitumor effect." (PMID 38137888, 2023). "Furthermore, the effect of IL-1β-induced PD-L1 in tumor cells on activated PBMCs was evaluated in cytotoxicity assay." (PMID 37441079, 2023).
tumor (continued). "The mRNA expression levels of genes characteristics of a tumor-supportive macrophage phenotype, including Arg-1, were also downregulated by shMYBL2-CM, while those of the cytotoxic response-related genes IL-1β, IL-12 A, and CD86 were increased by supernatants of shMYBL2 cells." (PMID 37865750, 2023). "It has been reported that brain metastatic tumor cells could trigger the transformation of astrocyte phenotype through the IL-1β-mediated NF-κB pathway to induce c-Met activation in tumor cells and promote their survival and growth." (PMID 36859173, 2023). "Furthermore, chemotherapy‐treated tumor cells which are dying release active IL‐1β, provoking the recruited neutrophils to form NETs in lung metastases." (PMID 38062888, 2023). "Furthermore, IL-1β plays a crucial role in the promotion of tumor metastasis., Primary contribution to treatment failure." (PMID 38066523, 2023). "However, genetic deletion of both IL-1α and IL-1β results in decreased recruitment of lymphoid cells and loss of IFN signaling in immune cells, allowing the tumor to escape immune control and worsen survival." (PMID 37733448, 2023). "M2 macrophages are associated with high expression of IL-10, IL-1β and vascular endothelial growth factor (VEGF) in vivo, and form a beneficial survival environment for tumor cells by suppressing immunity and promoting tumor angiogenesis, invasion and distant metastasis." (PMID 37901223, 2023). "IL-1β activates NF-κB signaling in tumor cells in a GBM subtype–specific manner." (PMID 37733448, 2023). "This shows that macrophage AIM2 is important for IL-1β secretion in response to tumor CM." (PMID 37449203, 2023). "NOD-like receptor family pyrin domain containing 3 (NLRP3) inflammasome activation within the tumor microenvironment can induce the activation of IL-1β, which subsequently activates RORγt to promote the secretion of IL-22 by Th17 cells, thereby promoting disease advancement." (PMID 37680632, 2023). "In this study, we identified that chronic exposure to HDM activates the NLRP3 inflammasome in macrophages, increases the production of IL-1β in the lungs, induces a pro-tumor lung microenvironment, and accelerates LC development and progression in two different mouse models." (PMID 36670473, 2023). "Besides, IL‐1β provokes hyperactive DCs to foster tumor lysates as immunogens and attach them to lymphocytes to trigger cytotoxic CD8+T cell responses peculiar to the antigen." (PMID 37752941, 2023). "The potential for HA to modulate the PDAC TME is also supported by our work identifying the direct effect of sEVs from HA-expressing tumor cells on normal monocytes where HA depletion resulted in a switch from hyperinflammatory (IL-1β) to a chemotactic (MIP1β) cytokine production." (PMID 37834100, 2023). "Collectively, these data suggest that HDM could accelerate lung tumor progression by activating the NLRP3/IL-1β signaling pathway and by creating a pro-tumor lung microenvironment rich in IL-1β+-macrophages, MDSCs, and PD-1+-myeloid cells." (PMID 36670473, 2023). "In addition, a synergistic antitumor effect was achieved when combining the IL‐1β and PD‐1 blockade in the LLC tumor‐bearing mouse model, and anti‐IL‐1β antibodies also reversed the suppressive TIME of LLC tumors." (PMID 37009412, 2023). "The pro‐inflammatory cytokine IL‐1β could be triggered and released from macrophages (Mφ) by lactate derived from tumor cells." (PMID 37009412, 2023). "IL-1β, TNFα and iNOS were identified as markers of M1 macrophages that inhibited tumor progression." (PMID 37441589, 2023). "In this current study, we found that HCC tumor-bearing mice had higher serum levels of IL-1β, which could disrupt BBB and allow the bile acids to infiltrate the brain." (PMID 37400621, 2023). "IL-1β is also recognized as a tumor-promoting cytokine due to its pro-inflammatory properties." (PMID 37772231, 2023). "Like iNOS, IL-1β seems capable of exerting a dual role in tumorigenesis and tumor defense." (PMID 38187473, 2023).
tumor (continued). "Blockade of IL-1β activity by administration of canakinumab might thus be expected to antagonize the upregulation of PD-L1 on tumor cells." (PMID 37441079, 2023). "Furthermore, it has been established that tumor cells and CAFs crosstalk through nuclear factor KB (NF-κB) activated by paracrine-IL-1β." (PMID 37033960, 2023). "In BC, high levels of IL-1β showed various tumor-promoting impacts." (PMID 37762557, 2023). "The anti-tumor effects of co-inhibition of the IL-1β and PD-1/PD-L1 pathways may be due to dynamic changes in the TME." (PMID 37511306, 2023). "Further, a significant decrease was noted in IL-1β levels in the tumor tissue." (PMID 37528154, 2023). "The findings are consistent with elevated iNOS and IL-1β in tumor growth." (PMID 38187473, 2023). "Meanwhile, lactate released by tumor cells inversely triggers the secretion of IL‐1β in Mφ." (PMID 37009412, 2023). "The study also highlights the role of IL-1β in resistance to currently available treatment modalities and suggests that combined NF-κB and IL-1β targeted treatments may lead to reduced tumor formation and growth." (PMID 37511306, 2023). "In NSCLC patients, IL-1β levels are higher in tumor tissues than in adjacent normal tissue." (PMID 37985999, 2023). "We hypothesized that inflammasome activation-induced IL-1β release in astrocytes might contribute to tumor cell proliferation." (PMID 37749707, 2023). "Furthermore, treatment of these co-cultures with Anakinra or anti-IL-1β reduced the spheroid-outgrowth-enhancing effect of CAFs, while their effect on tumor spheres in the respective monocultures was negligible." (PMID 37460545, 2023). "However, evidence suggests that the IL-1β released by microglia binds the IL-1 receptor (IL-1R) on the surfaces of tumor cells and activates downstream pathways that promote tumor cell proliferation." (PMID 36880534, 2023). "For example, an increased expression of IL-1β has been shown to promote the accumulation of myeloid-derived suppressor cells (MDSCs), decrease the number of natural killer (NK) cells, and increase tumor size." (PMID 37511306, 2023). "IL-1β and IL-6 correlate with the tumor extent and with the presence of lymph nodes." (PMID 38137862, 2023). "In addition, IL-1β contributes to tumor initiation and progression mainly by inducing chronic inflammation, promoting angiogenesis, as well as navigating MDSCs expansion and migration." (PMID 38304256, 2023). "Factors involved in tumor-mediated NET formation include tumor-derived inflammatory and chemoattractant cytokines (IL-8, IL-6, TNF-α, G-CSF and IL-1β), tumor extracellular vesicles, tumor-activated platelets, tumor-derived HMGB1, KRAS oncogene mutation and hypoxia." (PMID 37511453, 2023). "Macrophages are adept at phagocytosis, and whether their phagocytosis of live tumor cells is enhanced upon blockade of TNFα, IL-1β, or IL-6 is unknown." (PMID 37461742, 2023). "The IL-1β triggers an inflammatory cascade throughout the body and drives tumor metastasis." (PMID 36891151, 2023). "In agreement with a previous study, we found that budesonide inhibits NLRP3 and decreases IL-1β production by macrophages, which could explain, at least in part, its anti-tumor effect." (PMID 36670473, 2023). "Furthermore, inhibition of NF‐κB by BAY11‐7085 blocked the IL‐1β‐induced CCL2 secretion from tumor cells in different types of cancer cells." (PMID 37009412, 2023). "IL-1β expression was detected by IHC and qRT-PCR in tumor tissues of each group." (PMID 37434430, 2023). "On the one hand, pyroptosis can secrete IL-1β and IL-18 to trigger inflammatory responses and recruiting immune cells, which might enhance the anti-tumor effects of immunotherapy." (PMID 36941988, 2023).